PHLPP2 (PH domain and leucine rich repeat protein phosphatase 2)
Diseases named in the same sentence as PHLPP2 in open-access papers (continued):
Sharing a sentence is not in itself a finding about the gene and the disease.
tumor (continued). "A xenograft tumor model was constructed in nude mice to further explore the mechanism by which SNAI2 acts to activate the Akt pathway by inhibiting PHLPP2 in vivo." (PMID 35654777, 2022). "The findings indicated that overexpression of PHLPP2 significantly suppressed tumor sphere-forming capability." (PMID 35281874, 2022). "To reveal the underlying mechanism of PHLPP2 in regulating stemness, we first separated high (ROShi)- and low (ROSlo)-ROS subpopulations from HCT116 cells and measured their tumor sphere-forming ability." (PMID 35281874, 2022). "As a pleckstrin homology domain leucine-rich repeat protein phosphatase (PHLPP) isozyme, PHLPP2 is a critical regulator of cellular homeostasis and plays a tumor suppressor role in multiple human cancers 18-20." (PMID 35281874, 2022). "Several previous studies have identified miR-92a as being implicated in dysregulation and suppression of tumour suppressors, including PTEN and PHLPP2 in MCL models and VHL in CLL B-cells." (PMID 34899857, 2021). "In vivo and in vitro results further verified the tumor-suppressive role of PHLPP2 by inhibiting proliferation, migration, invasion, and EMT in tumor formation." (PMID 32633726, 2020). "As depicted in the results, tumor weight and volume in nude mice were reduced, moreover, the tumor growth was also inhibited in the PHLPP2, PHLPP2 + miR-141 and PHLPP2 + miR-424 groups compared with the NC-pcDNA group (all p < 0.05)." (PMID 32633726, 2020). "PHLPP1 and PHLPP2 have been identified as tumour suppressors because they can suppress of pro‐survival signalling, such as PI3K/Akt signalling pathway." (PMID 31863623, 2020). "PHLPP2 was unveiled as a tumor suppressor in multiple cancers acting as an inhibitor of AKT and inducing apoptosis of cancer cells." (PMID 33015182, 2020). "In conclusion, this study firstly suggests that MBNL1‐AS1 acts as a tumor suppressor of BC by targeting miR‐135a/PHLPP2/FOXO1 axis, providing a novel insight for BC diagnosis and treatment." (PMID 31769229, 2020). "Negative or weak levels of PHLPP2 immunoreactivity were observed in NSCLC tissue samples (64.9%), and PHLPP2 was clearly localized in the cytoplasmic and nuclear compartments of tumor cells." (PMID 31571378, 2019). "Further studies will continue to shed light on the functions and mechanisms of PHLPP2 as a crucial tumor suppressor in NSCLC." (PMID 31571378, 2019). "PH domain and leucine‐rich repeat protein phosphatase 2 (PHLPP2) has been reported to be a potent tumor suppressor in many human cancers." (PMID 31571378, 2019). "Both PHLPP1 and PHLPP2 are tumor suppressors and downregulated in many cancers, thereby maintaining Akt activity as well as promoting proliferation, growth, and survival." (PMID 31027321, 2019). "Our results revealed that PHLPP2 was significantly down‐regulated in the CRC tissues in comparison with adjacent non‐tumour tissue and the low expression of PHLPP2 was significantly related to poor survival." (PMID 31144439, 2019). "Here, we identified a novel pathway by which p27 inhibits BC cell invasion through another tumor suppressor, PHLPP2, in a MMP2-dependent manner." (PMID 29930380, 2018). "Pleckstrin homology domain leucine-rich repeat protein phosphatase 2 (PHLPP2) is a tumor suppressor that catalyzes the de-phosphorylation of the AGC kinases, while p27 acts as a tumor suppressor that regulates cell cycle, apoptosis, and cell motility." (PMID 29930380, 2018). "Previous studies showed that PHLPP2 acts as a tumor suppressor gene by modulating a number of critical tumor progression regulators, and it has been reported that PHLPP2 functions through an Akt-independent pathway." (PMID 28327189, 2017). "Among the predicted targets, PHLPP2 was chosen for further analysis because of its vital role in inhibiting tumor development and modulating cell proliferation and metastasis." (PMID 28327189, 2017).
tumor (continued). "The tumor suppressor genes, PHLPP2 and FOXO1, are the direct targets of miR-135a and transcriptionally downregulated by miR-135a." (PMID 25888950, 2015). "In marked contrast, the expressions of PHLPP1 and PHLPP2 were significantly decreased in 83.3% (115/138) and 82.6% (114/138) of tumor tissues, respectively (P<0.0001)." (PMID 25793736, 2015). "While PHLPP1 and PHLPP2 double knockout mice exhibit only a mild colitis resistance phenotype, their proposed repressive effects on Akt signaling have led to their designation as tumor suppressor genes." (PMID 40168118, 2025). "Consistent with the lack of somatic mutations in cancer, background mutation rates comparable to olfactory receptor genes, and no patterns of copy number loss in cancer, neither PHLPP1 nor PHLPP2 qualifies as a tumor suppressor." (PMID 40168118, 2025). "Furthermore, the IHC scores were negatively correlated between TRIM22 and PHLPP2 in both normal and tumor tissues." (PMID 38199981, 2024). "The results showed that positive staining of PHLPP2 was observed primarily in the cytoplasm of cancer cells, and high PHLPP2 protein expression was seen in 15.6% (29/185) of CRC tumor samples examined, whereas 54.5% (101/185) of normal tissues exhibited a strong PHLPP2 signal." (PMID 35281874, 2022). "Furthermore, the p-mTORC and p-Akt expression increased upon oe-SNAI2 but decreased following oe-PHLPP2 when compared to oe-NC in nude mice xenografted with tumor." (PMID 35654777, 2022). "Furthermore, the effect of PHLPP2 on tumor growth in vivo was analyzed by implanting oe-PHLPP2 or Lv-Cont HCT116 cells into nude mice." (PMID 35281874, 2022). "Moreover, oe-SNAI2 + oe-PHLPP2 resulted in alleviated tissue injury when compared to oe-PHLPP2 in nude mice xenografted with tumor." (PMID 35654777, 2022). "The results also confirmed overexpression of LINC00402, LINC00461, SFTA1P, and PHLPP2 or the inhibition of miR-141 and miR-424, could suppress the tumor growth (all p < 0.05)." (PMID 32633726, 2020). "HE staining also demonstrated that overexpression of LINC00402, LINC00461, and SFTA1P could enhance the inhibitory effect of PHLPP2 on tumor formation and metastasis." (PMID 32633726, 2020). "The in vivo results confirmed that MBNL1‐AS1 could block tumor formation of BC by decreasing miR‐135a and inducing PHLPP2/FOXO1." (PMID 31769229, 2020). "Low PHLPP2 expression in tumours predicted poorer overall survival." (PMID 31863623, 2020). "Furthermore, the nude mice in the PHLPP2 + miR-141 and PHLPP2 + miR-424 groups indicated the increased tumor weight and volume as well as a faster rate of tumor growth when compared to the PHLPP2 group (all p < 0.05)." (PMID 32633726, 2020). "Our IHC analysis results show that PHLPP2 plays a critical role in tumor cell metastasis." (PMID 31571378, 2019). "Based on our findings, PHLPP2 may function as a tumor suppressor by activating p62 transcription and expression, which further induces autophagy and promotes MMP2 degradation." (PMID 29930380, 2018). "Therefore, we have revealed a pathway by which the classical tumor suppressor p27 and the newly identified p27 downstream PHLPP2 coordinately suppress BC invasion." (PMID 29930380, 2018). "Based on the similar inhibitory effects on BC cell invasion exhibited by both p27 and PHLPP2, we sought to determine whether there might be a crosstalk between the two tumor suppressors." (PMID 29930380, 2018). "In addition, a remarkable relationship between miR-27a level and PHLPP2 level was observed in these tumor samples (r = −0.293, P = 0.039)." (PMID 28327189, 2017). "PHLPP2 has been found function as tumor suppressor in variety of malignancies." (PMID 25888950, 2015). "However, the expressions of PHLPP1 and PHLPP2 were significantly decreased in 83.3% (115/138) and 82.6% (114/138) of tumor tissues, respectively (P<0.0001, both)." (PMID 25793736, 2015). "Thus, the protein expression of PHLPP2 in tumor spheres obtained from HCT116 cells was determined." (PMID 35281874, 2022).
tumor (continued). "We applied four publicly available algorithms to call the potential miR-25-3p target genes and the results suggest that PH domain leucine-rich-repeats protein phosphatase 2 (PHLPP2), a tumor suppressor that inhibits cancer cell proliferation and invasion may be the target." (PMID 31015415, 2019). "Moreover, low PHLPP2 expression was significantly related to vascular invasion and tumor stage." (PMID 29209625, 2017). "However, the downregulation of the AKT3 gene in READ tumor indicated that the molecular mechanism underlying PHLPP2-associated READ progression might not be as simple as they appear, and should be examined carefully." (PMID 37737218, 2023). "A recent study has indicated that circ-ANAPC7 regulates the CREB-miR-373-PHLPP2 feed-forward loop via the PHLPP2-AKT-TGF-β signaling axis, thus inhibiting tumor growth and muscle wasting in pancreatic cancer." (PMID 36861443, 2023). "In the current study, for the first time, we found that PHLPP2 plays a tumor suppressor role by inhibiting the stemness of CRC cells and demonstrated that Nrf2 is a downstream target of PHLPP2-induced CRC stemness inhibition." (PMID 35281874, 2022). "GSCs transfected with oe-NC, oe-SNAI2, oe-PHLPP2, or oe-SNAI2 + oe-PHLPP2 plasmids were subcutaneously injected into the nude mice, with the tumor volume measured on a weekly basis." (PMID 35654777, 2022). "The results revealed that compared with oe-NC, the tumor weight and volume were significantly elevated in response to oe-SNAI2, but were decreased following oe-PHLPP2." (PMID 35654777, 2022). "It was found that the upstream molecules PHLPP2 and PTEN of Akt1 affect its phosphorylation process, which in turn affects the PI3K/Akt signaling pathway, and exerts an anti-tumor effect." (PMID 33692692, 2021). "The nude mice were inoculated with PHLPP2 and lncRNAs (LINC00402, LINC00461, and SFTA1P) or miRNA antagomir (miR-141 antagomir and miR-424 antagomir) into the right tumor, nine days after tumor formation." (PMID 32633726, 2020). "PHLPP2, an isoform of the PHLPP, has been reported to induce cell cycle arrest and apoptosis and to suppress tumor metastasis of various types of cancer." (PMID 28327189, 2017). "For example, MicroRNA-30b can function as a tumor suppressor in CRC by targeting KRAS, PIK3CD and BCL2, while MicroRNA-224, a tumor promoter, targets PHLPP1 and PHLPP2, sustains Wnt/β-catenin signaling and promotes aggressive phenotype of CRC." (PMID 29118671, 2017). "After X-ray radiation, Z138c cells with over-expression of miRNA-17-92 showed down-modulated tumor suppressors PTEN and PHLPP2 and enhanced pAkT as determined by western blot." (PMID 21040528, 2010). "In NSCLC, PHLPP2 was also found to be downregulated in tumor as opposed to what was observed in nontumor from TCGA and GSE81089, GSE40419, and GSE19804 datasets." (PMID 31571378, 2019). "IHC analysis also showed that PHLPP2 expression was lower in GC tissues than in non-tumor tissues and that high malignant-degree tumor tissues have lower PHLPP2 expression." (PMID 28327189, 2017). "PHLPP1 and PHLPP2 mRNA transcript levels were significantly lower in tumor samples than in paired adjacent nontumor mucosae (P<0.0001, both)." (PMID 25793736, 2015).
tumor (continued). "PHLPP2, an isoform of PHLPP phosphatases, has been reported to induce cell cycle arrest and apoptosis and suppress tumor growth by directly dephosphorylating and inactivating of Akt at Ser473 specifically and depressing the activity of PI3K/Akt signaling pathway subsequently." (PMID 25823655, 2015). "So, the expressions of both PHLPP1 and PHLPP2 mRNAs in tumor samples were much lower than in adjacent nontumor mucosae." (PMID 25793736, 2015). "Furthermore, we found that cancer genomics data do not support the proposed role of PHLPP1 or PHLPP2 as tumor suppressors." (PMID 40168118, 2025). "PHLPP2 was downregulated in the READ tumor samples as compared with the nontumor adjacent tissues." (PMID 37737218, 2023). "Additionally, the decreased expression of PHLPP2 within the tumor tissues was found to bear a negative correlation with the expression of miR-509-3p within the same clinical samples (r = − 0.479, p = 0.0154)." (PMID 35361144, 2022). "It was PHLPP1 but not PHLPP2 that was significantly related to the tumor T stage (P = 0.047)." (PMID 25793736, 2015). "It was PHLPP1 but not PHLPP2 that was significantly related to the tumor T stage." (PMID 25793736, 2015). "A positive correlation between miR-25-3p and METTL3 RNA levels and a negative correlation between PHLPP2 RNA levels and miR-25-3p or METTL3 RNA levels were detected in both PDAC and non-tumor pancreatic tissues from smokers and nonsmokers." (PMID 31015415, 2019). "Since we could not measure any detectable phosphatase activity of PHLPP2, we investigated the evidence for the role of PHLPP1 or PHLPP2 as tumor suppressors." (PMID 40168118, 2025). "In addition, a positive correlation between METTL3 and p-AKT or p-p70S6K levels and a negative correlation between PHLPP2 and METTL3 or p-AKT or p-p70S6K levels were observed in non-tumor pancreatic tissues from smokers and nonsmokers." (PMID 31015415, 2019). "We also detected METTL3, PHLPP2, p-AKT, and p-p70S6K protein levels in non-tumor pancreatic tissue samples from smokers and nonsmokers and found that all of them were significantly higher in smokers than in nonsmokers, except for PHLPP2 that was lower in smokers compared with nonsmokers." (PMID 31015415, 2019).
cancer (44 papers, 2014 to 2025). A tumor composed of atypical neoplastic, often pleomorphic cells that invade other tissues. "In summary, there is scant evidence from disease genotypes, clinically reported variants, or GWASs to support that dysregulation of either PHLPP1 or PHLPP2 is associated with cancer." (PMID 40168118, 2025). "We observe that PHLPP2 also targets phospho-AMPK in solid tumor-derived cancer lines, although differences in the impact of PHLPP2 loss on their responses to glucose limitation suggest different roles for AMPK in the cell lines." (PMID 34608126, 2021). "Akt phosphorylation itself is regulated by PHLPP1 and PHLPP2 phosphatases, and their impaired function is linked to cancer." (PMID 31027321, 2019). "Whereas PHLPP1 loss has been shown in a variety of cancers, PHLPP2 expression and role have remained largely unexplored." (PMID 24553260, 2014). "Therefore, we identify the novel molecular mechanisms underlying the anti-cancer activity of Chel A compound by targeting PHLPP2/JNK-c-Jun apoptotic axis." (PMID 27556506, 2016). "Somatic mutation of PHLPP2, however, occurs quite rarely in human cancers." (PMID 25823655, 2015). "Collectively, such outcomes emphasize diverse roles of ubiquitination in adjusting PHLPP2, whereas underscore its critical impact on various aspects of cancer biology." (PMID 41000374, 2025). "Evidence has emerged that the expression of the tumor suppressor PHLPP2 is ubiquitously lost in several cancers, including CRC." (PMID 35361144, 2022). "Analysis showed that the mean mRNA expression of PHLPP2 was lower in cancer samples than in normal tissue." (PMID 31863623, 2020). "While PHLPP2 has been identified as a target gene of various miRNAs, playing a crucial role in cancer cell proliferation and apoptosis." (PMID 32633726, 2020). "To further evaluate how PHLPP2 down-regulation mediated the Chel A anti-cancer activity, we checked the effect of PHLPP2 overexpression on Chel A-induced cancer cell apoptosis and anchorage-independent growth." (PMID 27556506, 2016). "Meanwhile, the PHLPP2 gene resides at the chromosomal location 16q22.3, which is frequently lost in multiple cancer types." (PMID 25823655, 2015). "Down-regulation of PHLPP1 and PHLPP2 proteins has been found in a variety of malignant tumors, including colorectal cancer, prostate cancer, and chronic lymphocytic leukemia (CLL)." (PMID 26245343, 2015). "Our results reveal PHLPP2 as a new biomarker of cancer progression, and implicate it as major negative regulator of NF-κB signaling." (PMID 24553260, 2014). "We show that PHLPP2 interacts with IKKβ kinase, decreases its phosphorylation and the subsequent NF-κB activation in cancer cells." (PMID 24553260, 2014). "PHLPP1 and PHLPP2 have previously been reported as protein phosphatases that specifically inactivate Akt, a pro-growth and survival kinase hyperactivated in many human cancers." (PMID 40168118, 2025). "PHLPP2 expression is considerably downregulated in various human cancers." (PMID 35308140, 2022). "PHLPP2 has also been reported to regulate Akt isoforms specifically in cancer cells." (PMID 36376971, 2022). "PHLPP2 functions as a sensor of glucose availability in primary tissue, such as pancreatic beta cells, and our study suggests it plays a similar role in some cancer cells." (PMID 34608126, 2021). "PHLPP2 had been reported as a therapeutic target for cancer and cardiovascular diseases." (PMID 33953793, 2021). "PHLPP2 dephosphorylates pAMPK in several other human cancer cells as well." (PMID 34608126, 2021). "PHLPP2 was also described as a survival and proliferation related suppressor in various cancers." (PMID 29209625, 2017).